IFNG (interferon gamma)
Diseases named in the same sentence as IFNG in open-access papers (continued):
Sharing a sentence is not in itself a finding about the gene and the disease.
infection (continued). "At a multiplicity of infection (MOI) = 1, in each of 3 independent experiments, we observed loss of IFNγ-dependent control of Mtb replication in the independently-derived TFEB-deficient RAW 264.7 macrophage lines from the two laboratories." (PMID 32574211, 2020). "Infection of T. gondii elicits the production of interferon gamma (IFN-γ), tumor necrosis factor (TNF), interleukin 10 (IL-10), IL-12, and several cytokine receptors, while reduces production of nitric oxide." (PMID 33330132, 2020). "Autophagy activation during infection is regulated by cytokines such as interferon gamma (IFN-γ) and pathogen recognition receptors (PRRs) that recognize conserved components of pathogens (PAMPs)." (PMID 32937909, 2020). "Early in the course of infection, cytokines, such as interleukin‐12 (IL‐12), stimulate interferon gamma (IFN‐γ) production, which triggers the response of T‐helper‐1 (Th1) lymphocytes and activates macrophages." (PMID 32100374, 2020). "Interleukin 12 (IL-12p70) and interferon γ (IFNγ) increased in blood during early infection; acute infection was marked by elevated circulating natural killer (NK) cells, neutrophils, and B cells, as well as increased tumor necrosis factor (TNF) and IL-10." (PMID 33021470, 2020). "Severe systemic inflammation upon infection leads to the production of excessive pro-inflammatory cytokines like IL-6, IFNγ, and TNFα." (PMID 33182754, 2020). "Our results with IFNγ feedback showed that at day 3 of infection, IFNγ is successfully able to rescue pathogen colonization in stopΔIEC mice." (PMID 32330185, 2020). "γδ T cells produced cytokines ex vivo at day 2 post infection, while virus reactive IFNγ producing γδ T cells were detected from day 7 post infection." (PMID 33603740, 2020). "In our model, Sts‐/‐ monocytes that are recruited to peripheral tissues during the early stages of infection respond more acutely to IFNγ and clear the infection more effectively, in part by deploying increased levels of antibacterial NO." (PMID 32841534, 2020). "In order to determine the effect of IFNγ priming on EPEC-induced cell death, we pretreated the SNU-C5 monolayer with IFNγ 24 h prior to infection." (PMID 33378358, 2020). "The combination of IFNγ and IFNα/β secreted at the site of infection also work synergistically both in vitro and in vivo to limit HSV-1 replication." (PMID 32708188, 2020). "Treatment was successful despite pre-existing multiple life-threatening infections; in particular, during blockade of IFNγ with emapalumab, all infections resolved with supportive antimicrobial medications and cessation of etoposide and dexamethasone." (PMID 33424859, 2020). "Interferon alpha (IFN-α) and interferon gamma (IFN-γ) were evaluated by ELISA test in sera from sows at different time-points after infection." (PMID 32295279, 2020). "In line with that, the adoptive transfer of an IFNγ-producing T cell line generated from immune BALB/c mice after sublethal infection with O. tsutsugamushi Gilliam conferred protection against lethal intraperitoneal challenge with the homologous strain." (PMID 33091016, 2020). "A significantly increased proportion of IFNγ-releasing CD4+ T cells was detected when splenocytes were co-cultured with lung cells from the 84-day infection with the treatment of isoniazid group relative to the untreated control group." (PMID 32411131, 2020). "CD4+ T cells from C57BL/6 as well as from BALB/c mice express huge amounts of IFNγ and lower amounts of TNFα in the infection with R. typhi with a peak response around day 7 postinfection, which is similar to the CD8+ T cell response." (PMID 33091016, 2020). "As expected, pre-infection of HFFs with TgRH88 tachyzoites or TgVEG sporozoites significantly suppressed IRF1 activation in response to IFNγ treatment (P<0.05), while prior infection with N. caninum tachyzoites did not." (PMID 32574210, 2020).
infection (continued). "We observed a substantial increase in serum IFNγ levels 8 days post-infection in 4E KI mice compared to their WT counterparts." (PMID 33014898, 2020). "Infection of IFNγ‐primed human THP1 cells with L. monocytogenes strain 10403S results in enhanced NLRP3 activation assisted by the IFNγ‐inducible GBP5." (PMID 32185892, 2020). "By this time post-infection, as more T cells began expressing IFNγ, only 7% of the IFNγ+ lymphocytes were NK cells." (PMID 31900030, 2020). "Further, our study findings indicate that CPLE treatment modulates the infection induced cytokine levels of TNFα, IFNγ, IL6 and IL4." (PMID 32074143, 2020). "Whereas in unstimulated WT macrophages the number of bacteria remained largely unaltered, priming of the macrophages with IFNγ 18 h prior to infection resulted in a remarkably decreased bacterial load at day 7 of culture." (PMID 32408806, 2020). "The production of adaptive cytokines by PBMCs, such as IFNγ and IL-17A, detected after 7 days of infection, was also compromised following the blockade of glycolysis." (PMID 32385235, 2020). "In brief, this involved M1-polarizing naive macrophages by incubation with IFNγ for 24 h, then mock or Cn-infection with complement- (provided by 20% GS) and 18B7-opsonized yeast at an MOI of 3:1." (PMID 32857777, 2020). "A population of IFNγ positive innate CD19+ B cells were transiently recruited to the airways at day 2 post-infection, and this was significantly increased in Peli1−/− animals." (PMID 32984077, 2020). "The proportion of infection-elicited IFNγ+, IL4+ and polyfunctional CD4+ T-cells among influenza A/H1N1-infected patients were significantly greater than vaccine-elicited CD4+ T-cells against influenza A/H1N1 (p = 0.033, 0.026 and 0.042 respectively)." (PMID 32572168, 2020). "The increased IFNγ produced within Sts−/− BMM cultures only occurred following infection with live pathogen, as treatment of cells with heat‐killed bacteria yielded undetectable levels of IFNγ production." (PMID 32841534, 2020). "In particular during early infection, it was indeed shown that the first cells to respond with a significant IFNγ secretion are NK cells, subsequently followed by NKT cells and only later by Th1 CD4+ T cells and CD8+ T cells." (PMID 32218784, 2020). "Interferon-gamma treatment and infection with various intracellular pathogens have opposing effects on macrophage survival." (PMID 33290416, 2020). "IFNγ is detected in the acute phase of the infection and is detected throughout the course of infection." (PMID 32438744, 2020). "In line with that, immune CD4+ T cells act on MΦ in the infection with R. typhi and activate the bactericidal activity of these cells via the release of IFNγ and TNFα." (PMID 33091016, 2020). "Further, androgenized mice exhibited decreased local IFNγ and TNFα along with increased CXCL1 and G-CSF, associated with decreased local M1:M2 macrophage ratios throughout infection." (PMID 32849562, 2020). "In contrast, our results indicate that whereas Trail−/− NK cells exhibit lower Ly49H expression than WT cells during LCMV‐WE infection, they show increased IFNγ production." (PMID 31742873, 2020). "We demonstrate that Sts−/− monocyte cultures produce elevated levels of interferon‐γ (IFNγ) after infection, relative to wild type cultures." (PMID 32841534, 2020). "We evaluated the effects of IFNα, IFNβ, and IFNγ on the infection and replication phases of C. trachomatis developmental cycle in an in vitro infection model of primary human synovial fibroblasts." (PMID 32050567, 2020). "Studies of ZIKV-infected patients have indicated higher expression of IP-10 and IFNγ in peripheral blood during acute infection, while serum levels of IFNγ were reduced during the convalescent phase." (PMID 33378361, 2020). "TOXO infection elicits an induction of the cytokine interferon gamma (IFNγ), which in turn inhibits TOXO replication by depletion of tryptophan (TRYP)." (PMID 33329089, 2020).
infection (continued). "Infiltrating macrophages are also involved in the early production of IFNα and IFNβ, and at later stages of infection secrete IL12 to further enhance the production of IFNγ by NK cells." (PMID 32708188, 2020). "RM35 ADSC were infected in a 12-well plate with 10,000 L14 VV, in the presence of increasing doses (ng/ml) of IFNγ or IFNβ added at the time of infection or 24 h earlier." (PMID 30917829, 2019). "To further validate the link between higher NKT infection-induced state, IFNγ and infection control, we infected PBMCs from these eight individuals with Salmonella (four WT and four TLR10 individuals) and measured intracellular bacterial load by CFU." (PMID 31332193, 2019). "The earlier study used bMDM primed with LPS and IFNG before infection, used a lower MOI and reduced IL10 levels using a neutralizing antibody." (PMID 31527895, 2019). "It seems that in the control and vaccine 1 group, infection triggered IFNγ-producing T cells, which resulted in tissue cysts." (PMID 31620134, 2019). "We employed the IFNγ secretion ELISPOT assay to characterize the early immune response developed in the spleen subsequent to murine infection with Francisella tularensis, Bacillus anthracis, Yersinia pestis and Influenza." (PMID 31443439, 2019). "For the first time, our findings provide a clue for exploring the effects of IFNG/IFNGR1 SNPs on the prevalence of TB beyond the control of infection acquisition." (PMID 31687049, 2019). "HeLa cells were infected with C. burnetii and treated with increasing concentrations of IFNγ at 6h post infection (pi)." (PMID 31461509, 2019). "IL8, IFNα, IFNβ, and IFNγ mRNA exhibited a wide range of activation after infection with these four H5N6 viruses." (PMID 31717638, 2019). "Here, the potential of cell-based immunoassays for early pathogen detection was evaluated by quantification of specific, antigen-activated, low-frequency IFNγ-secreting cells in mouse spleens following infection with various pathogens." (PMID 31443439, 2019). "For example, IFNG mRNA levels were on average 5.5 times higher in response to G18 infection when IL10 was knocked-down." (PMID 31527895, 2019). "These assays confirmed the requirement for IFNγ‐priming and the initiation of membrane damage ~ 6 h post‐Tg infection." (PMID 31268602, 2019). "Still, proinflammatory cytokines IFNγ and IL-17A were dominant, depicting an effort of host defense to overcome infection." (PMID 31318916, 2019). "We examined fitness in vitro, in standard Middlebrook 7H9 medium, using a direct competition assay; inside interferon-gamma-stimulated or naive human monocyte-derived macrophages, and finally, in vivo in a mouse model of infection." (PMID 31519879, 2019). "At 12 h after the infection, interferon-gamma, interleukin-10, interleukin-17A, interleukin-1 beta, interleukin-6, and tumor necrosis factor alpha (TNF-α) tended to be suppressed with micafungin treatment in both PF and control mouse models." (PMID 31249356, 2019). "The IFNγ immunoreactivity observed in the present study suggests IFNγ plays a role in the infection's neuropathogenesis also in CeMV-infected dolphins." (PMID 30936878, 2019). "HIF-1α also regulates the inflammatory response and NO production in IFNγ-activated macrophages against infection." (PMID 31681793, 2019). "Th1mediated cytokines such as interleukin (IL) 12, tumor necrosis factor alpha(TNF-α) and interferon gamma (IFN-γ) have been shown to be critical for thecontrol of this infection." (PMID 31130996, 2019). "Different studies confirmed that IFNγ is able to restrict C. trachomatis growth in cell culture models of infection." (PMID 31024512, 2019). "In infected mice, approximately 70 and 400 spots representing individual IFNγ-secreting cells per 106 splenocytes, were detected on days 3 and 4 post infection, respectively." (PMID 31443439, 2019).
infection (continued). "The critical requirement of IFN-γ during C. rodentium infection has been highlighted by the observations that IFN-γ knockout (Ifnγ-/-) mice had an impaired ability to clear infection." (PMID 30818341, 2019). "We found that 24 h post‐infection with both Tg strains IFNγ‐primed macrophages underwent enhanced cell death, as measured by lactate dehydrogenase (LDH) and XTT dye assays." (PMID 31268602, 2019). "Listeria monocytogenes was reported to induce IFNβ expression, suppress the production of IFNγ and TNFα, thereby promoting infection." (PMID 30984149, 2019). "A third group of IL-7Rα− cells was RORα− and showed a hybrid phenotype that varied considerably between tissues, similar to CD11c+ IFNγ-producing NK cells reported previously in the liver after infection." (PMID 31128961, 2019). "The pre-activation of iNKT cells by αGalCerMPEG prior to the infection resulted in even higher frequencies of IFNγ+ lung ILC1s, whereas only a minor additional effect was observed for spleen-derived ILC1s." (PMID 31440243, 2019). "While C. tyzzeri produces robust infection in wild-type mice, this infection is significantly exacerbated in Ifnγ−⁄− mice." (PMID 31231045, 2019). "T. cruzi infected mice vaccinated with the Tc24+E6020-SE vaccine at 70 days post-infection have a two-fold increase in Tc24-specific IFNγ producing cells compared to the sham control group." (PMID 31145733, 2019). "This study demonstrated elevated IFNγ production suggesting the role of pro-inflammatory cytokines in mediating pathology at the site of infection." (PMID 31803193, 2019). "The authors evidenced that IFNγ was responsible for a dramatic alteration of the transcriptional program of monocyte progenitors in the BM early during infection and before terminal differentiation and egress." (PMID 31354722, 2019). "The mechanism of CD8 T cell mediated protection during the late stages of the acute infection can be attributed to their ability to produce IFNγ, which plays a pivotal role in immune-protection against T. gondii infection." (PMID 31119107, 2019). "In contrast, an increased expression of several mediators of adaptive immune responses, including IL13, TGFβ, and IFNγ, and the transcription factor forkhead box P3 (Foxp3) can be found already at the beginning of demyelination at 30 days post infection." (PMID 30669615, 2019). "Collectively, these results demonstrate that PBMC from T. parva-immune cattle produce IFNγ following ex vivo exposure to recombinant, mammalian-expressed Tp9, consistent with anti-Tp9 cellular immune response development during natural infection." (PMID 31110506, 2019). "Resistance to infection by Leishmania parasites is mediated by interferon gamma (IFN-γ) that stimulates macrophages to produce nitric oxide (NO) which is essential for leishmanicidal activity." (PMID 30642262, 2019). "Using Plasmodium chabaudi or P. yoelii 17X infection as models of blood stage infection, NK cell frequencies increase as does their production of IFNγ and TNF." (PMID 31533835, 2019). "Using the deconvolution algorithm, we revealed that TLR10 polymorphism is associated with attenuated infection-induced state of NKT cells and cell–cell signaling mediated by IFNγ following infection, which in turn influences infection phenotype." (PMID 31332193, 2019). "It has been thought that adaptive immunity itself dominantly works for secondary infection except for IFNγ from T cells." (PMID 32038650, 2019). "Generally, the classic IL-12/IFNγ axis applies to this infection as well as it does to other Apicomplexan infections." (PMID 30873151, 2019). "Disruption of IFNγ signaling during a murine infection with B. pertussis results in a lethal disseminating disease." (PMID 31507615, 2019). "Blood samples collected from F. tularensis-infected mice revealed the presence of IFNγ-producing activated cells within one week post infection." (PMID 31443439, 2019).
infection (continued). "A modest but significant increase in IFNγ was secreted by MDM at 4 days after infection in the presence of either 10 or 50% plasma obtained after AAT infusion compared to MDM and plasma obtained before infusion." (PMID 31293581, 2019). "ILC3s produced IFNγ in response to infection with Salmonella typhimurium and IFNγ/IL-17 in response to infection with the Helicobacter hepaticus." (PMID 30984202, 2019). "The frequencies of IFNγ+ lung ILC1s were significantly elevated upon infection, whereas splenic IFNγ+ ILC1s were only marginally increased." (PMID 31440243, 2019). "In contrast, IL10 only regulated a subset of these genes; TNF and IFNG, during infection with the M. bovis reference strain AF2122/97." (PMID 31527895, 2019). "Later reports based on experimental infection with type II FIPV-79-1146 and type I FIPV-KU2 inoculation demonstrated that expression of interferon-gamma (IFN-γ) by antiviral T cells was associated with resistance to the development of FIP." (PMID 31118053, 2019). "In response to M. tuberculosis or rIAV, CXCR6KO mice developed Th1 cells, but at the peak of the effector response in both infections, there were reduced numbers of lung Th1 cells secreting IFNγ and TNFα." (PMID 30899256, 2019). "The family of Gbp proteins is highly expressed upon IFNγ stimulation as well as following infections, for example with the protozoanToxoplasma gondii or the bacteriumListeria monocytogenes (Degrandiet al., 2007)." (PMID 31544161, 2019). "It is possible and reasonable to combine the IFNγ treatment with the maintenance of an anti-graft rejection treatment when an infection cannot be controlled." (PMID 31690258, 2019). "in mice was shown to be dependent upon IL-12 and IFNγ signaling because STAT4 and IFNγR2 deficient animals were more susceptible to infection." (PMID 30873151, 2019). "On day 13 post infection, the response was approximately 150 IFNγ-producing cells per 106 cells, with background response from non-stimulated cells (spontaneous IFNγ secretion) below 5 spots." (PMID 31443439, 2019). "Assessment of the vacuole:cell ratio and mean vacuole size indicated that THP-1s, HFFs, and HUVECs limit infection by IFNγ-dependent Tg killing, while HeLas and A549s do so by restricting replication." (PMID 30744806, 2019). "High levels of IFNγ were detected in samples taken from groups after immunization and after challenge infection; however, the level of IFNγ was almost twice as high in the challenged group." (PMID 31681308, 2019). "Interferon gamma (IFNγ) production during an infection is important to control pathogen replication and mediate an effective host response." (PMID 31544161, 2019). "Effector CD8 T cells are one of the important sources of IFNγ, which is responsible for controlling both the acute as well as the chronic phase of the infection." (PMID 31119107, 2019). "As a response, proinflammatory cytokines like interferon gamma (IFNγ), IL-6, IL-12, IL-17, and chemokines are released to the infection site." (PMID 31362451, 2019). "First, stage 1 HRMAn was used to ascertain the impact of varying concentrations of IFNγ (50–500 IU/ml) on Tg infection, killing, and replication." (PMID 30744806, 2019). "A decrease in C. burnetii luminescence was observed in the IFNγ-treated cells 3-days post-infection, consistent with a cessation of luciferase production by intracellular bacteria." (PMID 31461509, 2019). "On day 8 post infection, more than 10 fold higher response of 250–650 IFNγ-producing cells per 106 splenocytes was observed." (PMID 31443439, 2019). "Our current study echoes this point as the greater weight loss in WT mice corresponded to higher levels of pro-inflammatory cytokines, namely IL-6 and IFNγ at day 7 post-infection." (PMID 31539400, 2019). "Studies conducted years later suggest that while IFNγ plays a critical role in controlling T. gondii infection during the acute phase of infection, chronicity of the infection is contained by cytotoxic CD8 T cells." (PMID 31119107, 2019).